CD24 (CD24 molecule)
Diseases named in the same sentence as CD24 in open-access papers (continued):
Sharing a sentence is not in itself a finding about the gene and the disease.
tumor (continued). "The overexpression of CD24 has been documented in several tumor types and the activation of the CD24/Siglec-10 axis has been shown to promote tumor immune evasion through the suppression of the cytotoxic T cell function and macrophage-mediated phagocytosis." (PMID 36013184, 2022). "The specific mechanisms by which pyrotinib targets TSC2-deficient tumor cells were investigated in this study, as well as the interaction between EGFR and CD24." (PMID 36231025, 2022). "Therapeutic CD24 blockade with monoclonal antibodies has been studied in vitro and in vivo animal models that showed increased phagocytosis of cancer cells, tumor reduction, and improved survival." (PMID 36294907, 2022). "In fact, the CD44+CD24+EpCAM+ phenotype was reported to exhibit a 100-fold increase in the tumor-initiating capacity versus the other cancer cells, both in vitro and in vivo." (PMID 36142575, 2022). "In the LAM-derived tumor model, pyrotinib was also shown to inhibit the expression of CD24 and siglec-10 in the tumor microenvironment." (PMID 36231025, 2022). "In one study involving an attenuated LM strain, knocking out of the dal and dat genes and inserting of the human CD24 gene led to the regression of the subcutaneously inoculated Hepa1-6-CD24 cell-derived tumor and increased tumor-free survival in mice." (PMID 36587206, 2022). "Similar to SNAI2, the expression of CD24 dropped with the addition of tumor cells and reached its lowest point in SCCs." (PMID 36552039, 2022). "Collectively, CD24+MDSC-DCs achieved tumor growth inhibition by reducing the proportion of Tregs in tumor microenvironment (TME), which alleviated the immune suppression of the TME." (PMID 35707772, 2022). "Treatment with anti-CD24 mAb significantly inhibited tumor cell growth in a time- and dose-dependent manner by inducing CD24 degradation in vitro and in vivo." (PMID 35409274, 2022). "Though CD24 is primarily expressed on immune progenitor cells and lymphoid tissue, certain tumor types have been found to express CD24 at high magnitudes." (PMID 36031601, 2022). "For example, within Grade 2, relative to that in the non-tumour tissue, the expression of markers CD24, CDX2, CD45 and CK6 was higher in Patient 1, and CD44 was higher in Patient 1 and Patient 3, compared to the other samples in the same group." (PMID 36362433, 2022). "Previous preclinical investigations have shown that blocking CD24 has abundant potential in anti-tumor applications." (PMID 35978372, 2022). "In contrast, the ratio of CD44/CD24 expressed on CTRL tumor tissue was significantly high compared to the GEM group." (PMID 35892853, 2022). "The senescence-like fibroblasts also highly expressed F2R and CD24, implying a role in suppressing anti-tumor immunity." (PMID 36198671, 2022). "CD24 is especially upregulated in tumor cells, while SIGLEC-10 expression occurs in a subpopulation of macrophages in the TME, suggesting a potential cross talk between CD24 and SIGLEC-10." (PMID 35978372, 2022). "Antibody blocking and adoptive transfer experiments demonstrated that downregulation of regulatory T cells (Tregs) mediated the inhibition of CD24+MDSC-DCs on tumor growth." (PMID 35707772, 2022). "For tumor cells, CD24 was the most important intrinsic molecular providing a “don’t eat me” signal, meanwhile, SDC4 was the most important receptor for cytokine signaling." (PMID 36172359, 2022). "For VCAM1, EGFR and CD24 our findings were validated with healthy and tumor tissue data obtained from the Human Protein Atlas." (PMID 36221114, 2022). "The positive expression rate of CD24 in the tumor diameter ≥ 5 cm group is as high as 87.0%, which is significantly higher than that in the tumor diameter < 5 cm group." (PMID 35938128, 2022). "Among them, GON4L is a transcriptional regulator gene that has been reported to drive tumor growth through the YY1-androgen receptor-CD24 pathway." (PMID 36120364, 2022).
tumor (continued). "CD24/Siglec 10 interaction protects tumor cells from phagocytosis, as it transmits a “don’t eat me” signal." (PMID 36294907, 2022). "It acts as an innate immune checkpoint by interacting with its ligand CD24 present on tumor cells, leading to the functional inactivation of immune cells." (PMID 36135216, 2022). "Blocking CD24 or Siglec-10 with monoclonal antibodies can enhance the ability of macrophages to phagocytose tumor cells and slow tumor growth." (PMID 35418152, 2022). "The differences in levels of seven EMT-associated markers, Ki-67, DAXX, CD24, CD44, vimentin, laminin and PDX1 plus CgA and NSE (neuroendocrine markers) enabled a distinct molecular signature for each tumour grade to be generated." (PMID 36362433, 2022). "An increase in CD24 expression is not only notable for demonstrating a decrease in the stem cell population, but it can also be used as a drug target for promoting tumor cell clearing by macrophages in the tumor microenvironment." (PMID 34503062, 2021). "This group reported that just 100 CD44+CD24+ESA+ cells were sufficient to faithfully capture the full characteristics of the primary human tumour in an orthotopic mouse xenograft model." (PMID 33799834, 2021). "In vitro and animal models show the significance of CD24 expression in tumor initiation and cell proliferation, drug- resistance, adhesion to vascular endothelium and metastases formation." (PMID 33915986, 2021). "In the context of epithelial-associated differentiation, KLK3 was found to be downregulated in the CTCs compared to primary tumours in all four models, and CD24 was downregulated in BM18 and LuCaP105." (PMID 34206049, 2021). "CD24 is a marker of human glioma that can help tumor cells escape phagocytosis and worsen the disease." (PMID 34926460, 2021). "As reported, the CD44+CD24- subpopulation of PCa cells are stem-like cells that are responsible for colony and tumor initiation." (PMID 34242345, 2021). "The generator of key pro-tumorigenic PGE2, PTGES is significantly upregulated in ALDH+ cells and conversely downregulated in CD44+/CD24- sorted tumor cells." (PMID 35127497, 2021). "Amongst the human tumour compartment markers, EpCAM and E-Cadherin showed a strong positive correlation (ρ = 0.57) and together with CD24, marked human luminal epithelial tumour cells." (PMID 33790302, 2021). "Functional analysis in genetically engineered mouse models (GEMM) for PC has identified CD24 as a positive regulator of the Wnt/β-catenin pathway activated during tumor differentiation, with a specific function of surface CD24 in regulating EMT phenotypes." (PMID 34453639, 2021). "Of these, the protein levels in the refractory PCa tissues were the highest, suggesting the presence of ALDH+CD44+CXCR4+CD24+ tumour cells in human PCa tissues." (PMID 34247196, 2021). "The CD24 gene has raised considerable interest in tumor biology as a new prognostic factor and a biomarker for the early detection of cancer." (PMID 34575716, 2021). "Intriguingly, there have been reports on the inhibition of metastatic gene signatures, downregulation of Twist, and upregulation of β-catenin expression (via crosstalk with the Wnt/β-catenin pathway) correlating to the CD24 expression in tumor cells." (PMID 34453639, 2021). "In recent years, the CD24 gene has raised considerable interest in tumor biology as a new prognostic factor and as a biomarker for the early detection of cancer." (PMID 34575716, 2021). "Immunohistochemical analyses further confirmed the increased β-catenin protein levels in miR-146a expressing tumor specimens which is diminished upon either quercetin treatment or CD24 over-expression." (PMID 34712602, 2021). "Consistent with prior reports, CD24+Thy1+ tumor cells were enriched ~ 10-fold for TICs compared to non-CD24+Thy1+ tumor cell subsets." (PMID 34088357, 2021).
tumor (continued). "Barkal and colleagues found that the highly sialylated cell-surface protein CD24, which is overexpressed in ovarian and breast cancers, binds to Siglec-10 on macrophages, protecting tumor cells from phagocytosis." (PMID 33921986, 2021). "Collectively, these results indicate that CD24/AKT/β-catenin axis plays an important role in miR-146a mediated tumor growth in-vivo." (PMID 34712602, 2021). "In BC, the CD44+/CD24- subpopulation isolated from tumor xenografts displayed high expression levels of HH signaling molecules compared to more differentiated cell subsets." (PMID 34354950, 2021). "The NK cell activating ligand MICA/B showed higher expression in the MDA-MB-231 tumor tissue than in RT-R-MDA-MB-231 or CD24−/low/CD44+ tumor tissue." (PMID 34502547, 2021). "This redifferentiation process towards a more luminal epithelial fate of these tumor cells is accompanied by a substantial increase in the number of cells that exhibit high levels of CD24 and a marked reduction in CD49f." (PMID 34145248, 2021). "RNA sequencing data from TCGA and flow cytometry data from clinical breast and ovarian cancer patients demonstrated that tumor cells highly express CD24, while TAMs highly express Siglec-10." (PMID 34625124, 2021). "MEDI5117 also displayed robust activity against trastuzumab-resistant HER2 tumor cells by targeting the CD44+/CD24- population." (PMID 34354950, 2021). "Although CD24 has been extensively studied for its role in tumor growth, there are few reports identify CD24 as a therapeutic target." (PMID 34363319, 2021). "(B and C) Kaplan–Meier analysis of the DFS (B) and OS (C) of all patients in the testing group after they were stratified into ≥19.5% of CD44-/CD24- (n = 100) vs. <19.5% of CD44-/CD24- tumor cells (n = 121)." (PMID 34318746, 2021). "The frequency of BCSCs (Lin-CD44+CD24- cells) in tumor samples was expressed as a percentage of total tumor cells by flow cytometry." (PMID 34778599, 2021). "Consistently, CD24 blockade reduced tumor growth and increased survival in a MCF-7 cell xenograft mouse model." (PMID 33921986, 2021). "In cellular and animal assays, CD24 works as a pleiotropic stimulator of tumor cell proliferation, adhesion to extracellular matrix (ECM) components, motility, and invasion." (PMID 34453639, 2021). "As expected, we isolated ALDH+CD44+CXCR4+CD24+ cells from the tumour derived from the PDX model by cell sorting." (PMID 34247196, 2021). "This indicated the enhanced tumour-initiation abilities of ALDH+CD44+CXCR4+CD24+- PCa cells in vitro, under androgen-deprived conditions in vitro." (PMID 34247196, 2021). "Inoculation with 102 or 103 ALDH+CD44+CXCR4+CD24+-PCa cells produced the greatest tumour mass within the shortest time, as compared with three other sorted subpopulations." (PMID 34247196, 2021). "The enhanced plasticity of CSCs permits the distinct CD44+/CD24- or ALDH+ CSC populations to transition between the two CSC states which best fits the conditions of the tumor microenvironment." (PMID 35127497, 2021). "In a similar way, Siglec-10 knockout (which also eliminates the CD24–Siglec-10 interaction) leads to a macrophage-dependent decrease in tumor growth and increased survival rates." (PMID 34068967, 2021). "Our study, thus points towards the tumor-suppressor functions of CD24, supporting our previous observation of reduced CD24 expression in oral tumors compared to the normal tissue." (PMID 34712602, 2021). "The parameters analyzed were the size of the tumor, the proliferation index (Ki-67 expression), CD24, Claudin 3, and Claudin 4 expression." (PMID 34298771, 2021). "Similar results have been obtained for the surface marker CD24 hyperexpressed in ovarian cancer, whose macrophageal receptor Siglec-10 inhibits recognition of the tumor by the immune system." (PMID 34068967, 2021).
tumor (continued). "Apart from these pluripotency factors, membrane proteins CD24 and CD49f have also been described for their roles as cancer stem cell markers and/or in tumour resistance to chemotherapy." (PMID 34203746, 2021). "There were 11 DEGs associated with tumor cell differentiation and dedifferentiation between EGFP- CD44-/CD24- cells and EGFP+ CSCs and they included RHBDL2, HIST1H4H, DSCC1, ZNF710, ATP8B3, and others." (PMID 34318746, 2021). "L1-L5 were epithelial luminal-like tumour cells enriched for expression of E-Cadherin, CD24, ER and Keratin 8/1824,39." (PMID 33790302, 2021). "Whilst CD24 plays a pivotal role in influencing tumorigenesis, it exhibits diverse functions that primarily depend on tumor entities and its localization to the subcellular compartments." (PMID 34453639, 2021). "CD24 monoclonal antibodies have been reported to inhibit tumor growth and prolong the overall survival in the mouse models of metastatic cancers." (PMID 34363319, 2021). "(E) Kaplan–Meier analysis of the DFS in the testing group of TNBC patients with chemotherapy after they were stratified into ≥19.5% of CD44-/CD24- (n = 24) vs. <19.5% of CD44-/CD24- tumor cells (n = 35)." (PMID 34318746, 2021). "Xenograft tumor subjected to qRT-PCR analysis confirms the overexpression of miR-146a and CD24 in these cells while β-catenin is down-regulated." (PMID 34712602, 2021). "Genetic ablation and therapeutic blockade of CD24 resulted in a macrophage-dependent reduction of breast MCF-7 tumor growth in vivo and increased survival in xenograft mouse models." (PMID 34572013, 2021). "Collectively, our data demonstrate that orthotopic PCa tumour-derived ALDH+CD44+CXCR4+CD24+ cell compartment is a maintainable subpopulation of pluripotent PCSCs with more tumorigenic and metastatic potential than other isogenic PCa cells." (PMID 34247196, 2021). "Some patients with a higher frequency of CD44-/CD24- tumor cells and CSCs had the highest rate of postoperative metastasis in this population." (PMID 34318746, 2021). "The interaction of Siglec-10 with its ligand CD24 on tumor cells is a mechanism of tumor immune escape." (PMID 34198593, 2021). "It was also demonstrated that sEVs derived from ascites of OCs have potential as diagnostics, because they express tumor-intrinsic biomarkers, such as CD24 and EpCAM." (PMID 34571921, 2021). "Following their lead, other studies in different cancer types found CD24 expression to be a marker for the CSCs themselves, overexpressed on cells that maintain tumor initiating abilities." (PMID 33915986, 2021). "The authors of this study also showed that breast CSCs with a mesenchymal-like (CD44+/CD24–) phenotype reside at the invasive edge of the tumor, whereas a population of hybrid epithelial-mesenchymal (E/M) CSCs are localized within the tumor interior." (PMID 33681228, 2021). "As a result, inhibiting the interaction of CD24-Siglec-10 promotes the phagocytosis of CD24+ tumor cells by TAMs, and has been shown to increase survival in preclinical mouse models." (PMID 33260974, 2020). "In an earlier investigation, CD24+ cells were isolated from two patient samples, followed by injection of 4000 CD24+ cells into NOD/SCID mice, which led to higher tumor development capability than CD24− cells, supporting the tumorigenic property of CD24." (PMID 32466488, 2020). "We further found that the numbers of CD11c+CD11b−CD103+H-2Kb+ DCs which expressed high levels of CD86, XCR1 and CD24 but low levels of CD64 were significantly reduced in tumor-burdened lungs of KP7 mice compared to KP mice." (PMID 33257678, 2020). "NcRNAs have been demonstrated to play an important role in tumor growth, metabolism, and migration, as well as in regulating the expression of CD24." (PMID 32765491, 2020). "A population of CD24+ cells isolated from OC samples and cell lines was shown to display high expression of stemness-related genes, high tumor initiation and fast tumor growth along with increased sphere-forming ability." (PMID 32257947, 2020).
tumor (continued). "The latest studies show that CD24 on the surface of tumor cells interacts with Siglec-10 on the surface of immune cells to promote the immune escape of tumor cells." (PMID 32765491, 2020). "A significant example that CD24, a “Don’t eat me” signal on tumor cells, was found to be complementary to CD47." (PMID 33597922, 2020). "nIR signals at the wavelength of 700 nm from tumor cells and mammary epithelial cells (CD24-positive and CD45-negative cells) were measured." (PMID 32385408, 2020). "Since BCSCs were first identified in 2003 based on CD44 and CD24 expression, different biomarkers for BCSCs have been identified in BC patient tumor samples, animal models, and cell lines, indicating the existence of a variety of BCSC subgroups." (PMID 33327542, 2020). "Genetic ablation of CD24 in tumor cells, or antibodies targeting CD24, or Siglec-10, induces phagocytosis and obrogation of tumor growth." (PMID 32194856, 2020). "It has been proven that Wnt/ β-catenin plays an important role in tumor growth and regulating the expression of CD24." (PMID 32765491, 2020). "Simultaneously, the expression of CSC markers in the tumour tissues were enhanced by 30-, 150- 200-folds for CD24, CD133 and CD44, respectively, when compared to miPSCs." (PMID 32203212, 2020). "The CD24-linked nitric oxide (HN-01)-targeted delivery system was shown to induce apoptosis in CD24+ tumor cells after receptor-mediated internalization." (PMID 33260974, 2020). "CD24 is highly expressed in various tumor cells and is related to the occurrence and development, invasion, and migration of tumor cells." (PMID 32765491, 2020). "Second, CD24 has been associated with epithelial–mesenchymal transition (EMT), a multistep process enabling the tumor cells to invade and disseminate." (PMID 33260974, 2020). "Results revealed that the expression of stem cell markers identified as CD44, NANOG, OCT3/4, and CD24 in tumor cells was strongly attenuated by SR59230A treatment." (PMID 32093135, 2020). "Previous study of immunohistochemistry staining for CD24 on human HCC tissue samples as well as their non-tumor counterparts showed there were 0% to 16% in the HCC specimens, whereas there was no CD24 expression in the non-tumor counterparts." (PMID 32184801, 2020). "In one case, CD44+CD24- cell subsets were detected only in the primary tumor, and in other cases, only in the blood." (PMID 32316333, 2020). "For example, CD24 regulates the invasion of tumor cells by suppressing tissue factor pathway inhibitor-2 (TFPI-2) through a Src-dependent manner." (PMID 32765491, 2020). "Even after incubation with IL-6, the concentration of EpCam+CD44+CD24– tumor stem cells was 1.33 times higher in patient St23784/17 than patient Ti41749/17." (PMID 32523653, 2020). "CD24 has not only been correlated with clinicopathological parameters in EOC, but also associated with tumor grade and overall survival in several other cancers." (PMID 33260974, 2020). "In this regard, the most recently discovered “don't eat me” signal found to confer tumor cell resistance to phagocytosis is CD24, a heavily glycosylated cell surface protein known as heat stable antigen." (PMID 32508018, 2020). "As expected, we found that CD44+/CD24−/low/EpCam+ MDA-MB-468 cells had higher tumor-initiating ability in this model." (PMID 32183150, 2020). "The combination of CD24-expressing tumor cells and P-selectin on platelets can promote the excretion of tumor cells from the bloodstream and thus promote their metastasis." (PMID 32765491, 2020). "Our testing of oregano using the same model of chemically induced rat mammary carcinogenesis demonstrated decrease in CD24 and EpCAM expression in tumor cells." (PMID 32204409, 2020). "When the analysis was restricted to the luminal ER+ tumours, high BMI1 expression was associated with low expression of ALDH1A1 (P = 0.025), ALDH1A3 (P = 0.026), CD133 (P = 0.038), CD44 (P = 0.0001), CD24 (P = 0.004) and SOX10 (0.0006)." (PMID 32524353, 2020).